DGUOK-AS1 (DGUOK antisense RNA 1)
Gene: Long non-coding RNA gene on chromosome 2 (73,927,769 to 73,986,660, reverse strand). Ensembl gene ENSG00000237883.
Diseases named in the same sentence as DGUOK-AS1 in open-access papers:
DGUOK-AS1 is named in the same sentence as 1 disease in open-access papers, as found by Europe PMC text mining. Sharing a sentence is not in itself a finding about the gene and the disease. The quoted sentences say what the papers report.
liver cancer (1 paper, 2024). An epithelial or non-epithelial malignant neoplasm that arises from the liver. "In liver cancer cells, the insulin/DGUOK‐AS1/miR‐145‐5p axis did not alter the histone acetylation at the SIX1 promoter, suggesting that the insulin/DGUOK‐AS1/miR‐145‐5p axis may not regulate SIX1 expression at the transcriptional level." (PMID 39258807, 2024).